CCR2 (C-C motif chemokine receptor 2)
Diseases named in the same sentence as CCR2 in open-access papers (continued):
Sharing a sentence is not in itself a finding about the gene and the disease.
tumor (continued). "We then explored the effect of CCR2 blockade on Mφs polarization by separating CD14+ cells from the tumor mass and using quantitative RT-PCR to detect expression of Mφs polarization-associated genes." (PMID 31611552, 2019). "We transplanted SmoA1 CCR2+/+ tumours into Ccr2 wild-type (+/+), heterozygous (+/RFP), and homozygous knock-in (RFP/RFP) mice." (PMID 31160587, 2019). "More evidence also points toward an involvement of the CCL2/CCR2 axis in the crosstalk between tumor cells and macrophages leading to immunosuppression." (PMID 31921102, 2019). "The CCR2 antagonist RS504393 significantly reduced the tumor volume and weight compared with the control group (P < 0.05)." (PMID 31024838, 2019). "CCR2 inhibition retains monocytes in the bone marrow and reduces the number of TAMs in tumors, leading to decreased tumor burden and metastasis in different tumor indications." (PMID 31402908, 2019). "Using an orthotopic implantation model, we found that macrophage infiltration in tumour tissues was significantly reduced and survival time of tumour-bearing mice was decreased upon Ccr2 gene deletion." (PMID 31160587, 2019). "Tumor derived CCL2 has also been correlated with greater CCR2-expressing T cell trafficking in several different solid tumors." (PMID 30736355, 2019). "Blocking of CCR2 resulted in reduced tumor cell extravasation and inhibition of lung metastasis both in vitro (MC-38GFP cells) and in vivo models (Roblek al., 2015)." (PMID 31350989, 2019). "The C–C chemokine ligand type 2 and receptor (CCL2/CCR2) pathway is required for the mobilization of monocytes from the bone marrow into the tumor microenvironment." (PMID 31540435, 2019). "CCL2 has been reported to bind its receptors CCR2 and CCR4 on lymphocytes, resulting in recruiting immune cells to tumor sites, which causes immunosuppression." (PMID 31207928, 2019). "CCR2 KO mice showed reduced infiltration of inflammatory Mo/Mφ in tumor tissues and reduced vascular CXCR4 expression in HCC tumors." (PMID 30800123, 2019). "Blockade of the CCL2/CCR2 axis has exhibited efficacy in TAMs-related therapy with several preclinical tumor models." (PMID 31024838, 2019). "Meanwhile, the number of F4/80 labeled TAMs, the number of CD163 labeled M2 TAMs, and the Ki-67 index in the tumor tissues were significantly reduced in the CCR2 antagonist group than those in the control group (P < 0.01)." (PMID 31024838, 2019). "Combination therapy of CCR2 inhibitor PF-04136309 with FOLFIRINOX chemotherapy for PDAC restores the anti-tumor immune microenvironment, preventing CCR2+ monocytes from emerging from the bone marrow." (PMID 31474975, 2019). "There is considerable interest in developing therapies that target CCL2/CCR2 and tumor-resident myeloid cells." (PMID 31823764, 2019). "In an orthotopic model of murine PC, it was seen that inhibition of CCR2 by PF-04136309 promoted anti-tumor immunity." (PMID 30925924, 2019). "Collectively, these data suggested that targeting CCL2/CCR2 enhanced anti-tumor immunity in the residual tumor, thereby overcoming the resistance to immune checkpoint blockade therapy." (PMID 31780645, 2019). "Further analysis showed that the high expression of Nav1.6 was closely related to the one of CCR2\CCR4 in tumor lymph node metastasis." (PMID 31672162, 2019). "Immunofluorescent analysis revealed the presence of both GFP+ and RFP+ cells in the allograft tumour, indicating the presence of CCR2+ cells in the tumours." (PMID 31160587, 2019). "PCR analysis showed that the cells of the TME produced more than 30-fold higher Ccl2 and corresponding Ccr2 genes when compared to tumour cells." (PMID 31160587, 2019). "Macrophages are the effector cells of the innate immune system and express C-C chemokine receptor type 2 (CCR2) in response to CCL2 resulting in continuous recruitment of macrophages to the tumor sites." (PMID 31660078, 2019).
tumor (continued). "In prostate and breast cancer, CCR2 was found expressed by tumor cells and to promote cancer growth and migration." (PMID 30894861, 2019). "In the present study, we showed that the CCR2 antagonist treatment alleviates the tumor progression after iRFA and reverses the resistance of residual tumors to PD-1 therapy." (PMID 31780645, 2019). "It was reported that both small molecular inhibitors and antibodies targeting either CCL2/CCR2 or CSF-1/CSF-1R signaling axis obviously inhibited the mobilization of monocytes and macrophages accumulation in tumor sites." (PMID 31300030, 2019). "Egress of classical monocytes from bone marrow into peripheral blood is mediated by CCR2 signaling, which is also important for recruitment to tumor sites." (PMID 30776148, 2019). "Subgating CD45+ infiltrating cells by the myeloid-specific marker CD11b and the monocyte marker Ly6C allowed the identification of monocyte-derived cells inside the tumor that specifically express the chemokine receptor CCR2." (PMID 30949170, 2019). "Results indicate a decrease of intermediate monocytes but a significant increase of CCR2+ cells among the same subset, thus suggesting that this population is actively recruited at tumor site." (PMID 30813960, 2019). "Their results suggested that TAMs with defective CCR2 expression also demonstrated inhibited migration to the tumor, however TAMs were able to overcome this in the presence of complement component 5 (C5a)." (PMID 31354741, 2019). "On the other hand, Madsen and colleagues showed that CCR2+ MoD-TAM were responsible for collagen degradation in the TME in various tumor models." (PMID 31417566, 2019). "Bartneck and colleagues reported an accumulation of a distinct subset of macrophage, CCR2+ TAM at the stroma/tumor interface within a highly vascularized region in resected HCC." (PMID 31540435, 2019). "A second strategy to eliminate the immune suppressive tumor macrophage population is to prevent their recruitment to tumor tissues by administering agents that block signaling by the chemokine receptor CCR2." (PMID 32010120, 2019). "Tumor-resident MSCs release a large amount of various chemokines, including CCL-2, CCL-7 and CCL-12, thereby enhancing the recruitment of monocytes expressing CCR2 into tumor sites and increasing the number of macrophages and growth of tumors." (PMID 31336889, 2019). "CSF-1R and CCR2 antagonists have been reported to prevent infiltration of TAMs into the tumor mass increasing response to gemcitabine treatment in mouse models of PDAC." (PMID 30356656, 2018). "Collectively, these experiments demonstrate that CCR2+HSCs uniquely give rise to APCs that capture tumor antigen in vivo and cross-present tumor antigens to CD8+ T cells in vitro and in vivo." (PMID 30333482, 2018). "With chemotactic migration of CCR2, additional CCR2 expression enhanced tumor accumulation and anti-tumor effect." (PMID 30680249, 2018). "CXCR4, cooperate with chemokine receptor (CCR1 and/or CCR2) to promote metastasis-associated macrophage (MAM) accumulation and thereby metastatic tumor growth." (PMID 30190788, 2018). "We further demonstrate that this is associated with increased CCR2 expression by KLRG1+ NK cells from Ackr2−/− mice and attendant hyperresponsiveness of these cells to tumor-expressed CCL2." (PMID 30158126, 2018). "The chemokine (C-C motif) ligand 2 (CCL2) with its cognate receptor chemokine (C-C motif) receptor 2 (CCR2) plays important roles in tumor invasion and metastasis." (PMID 29934505, 2018). "The resulting dendritic cells derived from CCR2+HSCs were markedly superior in presenting tumor antigens in vitro over cells that arose from CCR2−HSCs." (PMID 30333482, 2018).
tumor (continued). "We believe that CCR2 expression by CCR2+HSCs is maintained until the cells cross the blood-brain barrier, but is then either downregulated or shed within the tumor microenvironment once they have differentiated into antigen presenting cells." (PMID 30333482, 2018). "The concentration of CCL2 in BC increases with advancing tumor stage, while a median level of CCR2 decreases with advancing stage." (PMID 30151375, 2018). "Phenotypic profiling of TC1 tumors revealed maximal expression of CCR2 by tumor resident MDSCs, and MCP-1 by transplanted tumor cells, tumor associated macrophages (TAMs) and tumor associated neutrophils (TANs) respectively." (PMID 30400822, 2018). "In these models, anti-CCL2 antibody treatment, or genetic deletion of CCR2 inhibits the monocyte migration to the tumor-challenged lung and decreases the number of MAMs, which results in the reduction of metastatic tumor burden." (PMID 30483271, 2018). "CCL2 and its receptor (CC chemokine receptor, CCR2) are pro-inflammatory mediators and chemoattractant that regulate the development and progression of tumor through migration and infiltration of monocytes or TAMs and CCL2/CCR2 axis." (PMID 29458367, 2018). "Given the observed correlation between the transfer of CCR2+HSCs and T-cell activation within the tumor microenvironment, we next conducted experiments to determine the phenotype and function of cells derived from CCR2+HSCs within the tumor microenvironment." (PMID 30333482, 2018). "This further confirms our observations that CCR2+HSCs are responsible for increased activation of tumor-infiltrating T-cells." (PMID 30333482, 2018). "It is also known to bind to its receptor (CCR2) on M1-type macrophages and activated NK cells to recruit them to the source of its origin like the brain and tumor mass." (PMID 30041669, 2018). "One of the major consequences of CCL2 expression by BC cells is the recruitment of CCR2 positive myeloid cells to the primary tumor which facilitates metastasis in general." (PMID 29930538, 2018). "The blockade of IFNγ using a specific antibody or the use of CCR2 deficient mice, which were subjected to UVB exposure, have decreased of macrophages infiltration in the skin and reduced tumor volume." (PMID 30420855, 2018). "The CCR2 antagonist also supported tumor-infiltrated CD8+ T cells by blocking TAM-mediated immunosuppression." (PMID 30410942, 2018). "Phenotype analysis determined that once the cells derived from CCR2+HSCs reach intracranial tumor after intravenous injection, they upregulate markers associated with antigen presenting cells, including CD11c, MHC-II, and CD80." (PMID 30333482, 2018). "By contrast, combining the oral CCR2 small-molecule antagonist PF-04136309 with conventional chemotherapy resulted in partial tumor responses (49%) with local tumor control in 97% of patients with advanced pancreatic ductal adenocarcinoma (PDAC)." (PMID 29594035, 2018). "One week later, vaccine-site draining lymph nodes were harvested and analyzed for relative expansion of DsRed+CD3+ T cells and demonstrated that CCR2+HSCs led to the expansion of tumor-reactive T cells in vivo." (PMID 30333482, 2018). "A total blockade of CCL2 both from the tumor and the stroma decreased recruitment of CCR2+ monocytes, inhibited tumor metastasis and extended survival time of tumor-bearing mice." (PMID 29934505, 2018). "Here the authors show that in the colon these macrophages are CCR2-dependent, while in tumours they gain the ability to self-renew, relying on CSF1 and promoting cancer progression." (PMID 29422500, 2018). "Further investigation revealed that the deletion of Rbpj in macrophages results in loss of CCR2 and TAM markers, suggesting a cross-talk between canonical Notch signaling and the CCR2/CCL2 signaling pathway in TAMs in the tumor microenvironment." (PMID 29686671, 2018).
tumor (continued). "To determine the relative amount of CCR2+HSC-derived cells vs. CCR2−HSC-derived cells that upregulate a suppressive phenotype, we injected 5 × 105 of either DsRed+CCR2+HSC or GFP+CCR2−HSC into tumor-bearing mice." (PMID 30333482, 2018). "The interaction between CCL2 and its primary receptor CCR2 is crucial for recruiting large numbers of monocytes to the tumor tissue." (PMID 30059519, 2018). "The cells that arose from both CCR2+HSCs and CCR2−HSCs after culturing in dendritic cell media were pulsed with tumor-RNA." (PMID 30333482, 2018). "It has been proved that blocking of the CCL-2/CCR-2 axis decreased macrophage infiltration and reduced tumor growth." (PMID 28660349, 2018). "In a mouse model of pancreatic cancer, treatment with a CCR2 antagonist decreases the infiltration of monocyte/macrophage in the tumour." (PMID 29963704, 2018). "RNA was isolated from tumors of mice that received adoptive transfer of tumor-specific T-cells concomitantly with either CCR2+HSCs or CCR2−HSCs." (PMID 30333482, 2018). "A substantial portion of TAMs are derived from CCR2-expressing circulating classical monocytes, which migrate to the tumor sites under the guidance of tumor cell-derived CCL2." (PMID 30597969, 2018). "Elevated CCL2 within the tumor microenvironment promoted the recruitment of C-C chemokine receptor type 2 expressing (CCR2+) myeloid cell types, including MDSC and TAM." (PMID 30042333, 2018). "The sensitivity of the tested parameters in the total cancer group was higher for CCL2 (64.95%) than for CCR2 (61.86%) and higher than for routinely used tumor marker CA 15-3 (59.79%)." (PMID 30151375, 2018). "We observed significantly enhanced tumor regression of MC38 tumors grown in CCR2−/− hosts treated by local IR as compared with tumors grown in wild-type (WT) mice (Day 31, CCR2−/− IR 52 ± 33 vs. WT IR 351 ± 82, P < 0.05: Student’s t-test)." (PMID 29170400, 2017). "Through the use of CCR2 knockout mice or an antibody against mCCR2, we observed that the anti-tumor response as a result of T cell priming was increased in mice treated with radiation, STING agonist, or both." (PMID 29170400, 2017). "CCR2-driven infiltration of γδT17 cells was consistent with upregulation of its major ligand CCL2 in tumours." (PMID 28580944, 2017). "It is interesting that while IL-1β, CCL2, and VEGF are secreted at high levels from hypoxic and/or MSCs-entrained IRISOE TNBC tumor cells, their receptors, IL-1R, CCR2, and VEGFR2 were only observed on MSCs, TAMs, and ECs, respectively." (PMID 29262555, 2017). "Here we identify that within the TRAIL secretome, CCL2 fulfils a central function in the formation of a tumor-supportive myeloid compartment that is achieved in vivo via the engagement of CCR2 on host cells." (PMID 28212753, 2017). "show that endogenous TRAIL signaling in cancer cells induces a FADD-dependent secretome that promotes the accumulation of M2-like immune cells and tumor growth via host CCR2." (PMID 28212753, 2017). "In tumor regression studies, triple treatment of anti-CCR2 + IR + cGAMP showed superior anti-tumor response compared with treatment with IR alone or IR + cGAMP (P < 0.05 for both: Student’s t-test)." (PMID 29170400, 2017). "Together suggest that CCL2 secreted by MSCs-entrained IRISOE TNBC tumor cells induces expression of its own receptor CCR2 on the surface of the low expressing THP1-macrophages." (PMID 29262555, 2017). "Our results demonstrate that CCR2 blockade in established tumors reverses radiation resistance and achieves greater anti-tumor efficacy." (PMID 29170400, 2017). "We observed that in a MC38 tumor model, the majority of CD11b+Ly6Chi cells are CCR2+, in that the baseline level of the CD11b+Ly6Chi population was lower in tumors grown in CCR2−/− mice compared with tumors grown in WT mice." (PMID 29170400, 2017). "For instance, despite inhibition of CCL2 or CCR2 within the tumor microenvironment was indicated to be beneficial in inhibiting metastasis." (PMID 29197379, 2017).
tumor (continued). "We employed CCR2 germ-line knockout mice to investigate the involvement of CCR2+Ly6Chi cells in the tumor radiation response." (PMID 29170400, 2017). "For instance, CAFs secrete CC chemokine ligand 2 (CCL2), which recruits macrophages to the tumor site through binding to its receptor CCR2." (PMID 28467800, 2017). "We profiled the tumor myeloid cell population on day 3 post-IR for all treatment groups: IgG isotype control, 20 Gy + IgG control, anti-CCR2 antibody, and 20 Gy + anti-CCR2 antibody." (PMID 29170400, 2017). "All treatment groups presented a significantly lower level of CCR2 protein expression compared with tumor group (p < 0.05)." (PMID 28587280, 2017). "The danger signals thereby induce the production of inflammatory cytokines such as PDGF, TNFα, CCR8, and CCR2 within the tumor microenvironment, and consequently enhance MSCs swarming into the tumor location(s)." (PMID 29326689, 2017). "In line with our results implicating FADD as crucial for TRAIL-R-mediated CCL2 secretion, 3LL FADD KO cells replicated our results observed in CCR2 KO mice regarding tumor burden and myeloid infiltrates." (PMID 28212753, 2017). "Most recently, it was shown that macrophage migration inhibitory factor (MIF)/CXCR4 and monocyte chemoattractant protein-1 (MCP-1)/CCR2 pathways are responsible for migration of MSCs in the tumor microenvironment of the lungs." (PMID 28798777, 2017). "Although these experiments identify host cell expression of CCR2 and tumor cell expression of TRAIL-R and CCL2 as required for this pro-tumorigenic crosstalk between the TRAIL/TRAIL-R and CCL2/CCR2 systems, the source for TRAIL can be many fold." (PMID 28212753, 2017). "Most importantly, when combining anti-CCR2 with IR treatment, tumor antigen-specific T cell priming was enhanced to a greater extent compared with either IR alone (P < 0.05: Student’s t-test) or CCR2 antibodies alone (P < 0.05: Student’s t-test)." (PMID 29170400, 2017). "The enhanced T cell function in CCR2−/− mice after tumor irradiation as well as after anti-CCR2 + IR treatment indicated that CCR2+Ly6chi monocytic MDSCs play an important role in T cell suppression in irradiated tumors." (PMID 29170400, 2017). "Here we reported that an extrinsic mechanism of tumor radioresistance is regulated by host CCR2+ M-MDSCs (CCR2+Ly6chi)." (PMID 29170400, 2017). "Taken together, we established a relationship between CCR2-expressing myeloid cells of hosts and tumor radioresistance." (PMID 29170400, 2017). "In in vivo solid tumor models (breast, gastric and ovarian cancers), it was shown that CCL2/CCR2 axis mediated the migration of MSC into the tumor and also showed evidence of CCL2-mediated protumor effect." (PMID 28045930, 2017). "After tumor inoculation, the expression of mRNA and protein levels for CCL2 and CCR2 in tumor group were significantly increased compared to the sham group (p < 0.01)." (PMID 28587280, 2017). "For instance, CCR2-expressing monocytes and macrophages can interact with tumor-derived CCL2 and aid the migration of macrophages to lung metastases in a breast cancer model." (PMID 28382036, 2017). "In summary, we describe a new immunosuppressive effect of STING following radiation that results in an influx of CCR2+ M-MDSCs that rescue tumors from the anti-tumor effects of radiation." (PMID 29170400, 2017). "In this report, we demonstrate that MDSC recruitment and tumor radioresistance rely on CCR2+ cells in the host." (PMID 29170400, 2017). "We did not observe a reduction in vessel density in either untreated control or irradiated tumor in CCR2−/− hosts, compared with WT mice." (PMID 29170400, 2017). "We performed tumor growth studies using IR + anti-CCR2 treatment while depleting CD8+ and CD4+ T cells." (PMID 29170400, 2017). "Treatment with anti-CCR2 antibodies alone had little effect on tumor regression, similar to untreated controls." (PMID 29170400, 2017).